SLC15A5 (solute carrier family 15 member 5)
Description:
Proton oligopeptide cotransporter.
Tractability: Antibody: UniProt predicts a signal peptide or a membrane-spanning region.
Gene: Protein-coding gene on chromosome 12 (16,188,485 to 16,277,685, reverse strand). Ensembl gene ENSG00000188991.
Subcellular location: Membrane
Gene Ontology:
Molecular function: protein binding; transmembrane transporter activity
Biological process: transmembrane transport
Cellular component: membrane
Genetic constraint (gnomAD): Loss-of-function variants: 46 observed, 44.01 expected, observed/expected ratio (o/e) 1.05, 90% interval 0.82 to 1.34. The upper end of that interval is the gene's LOEUF score, 1.34, which puts it in group 5 of 6, group 1 being the genes least tolerant of losing a copy. Missense variants: 637 observed, 636.46 expected, observed/expected ratio (o/e) 1, 90% interval 0.94 to 1.07. Synonymous variants: 249 observed, 243.94 expected, observed/expected ratio (o/e) 1.02, 90% interval 0.92 to 1.13.
Homologues: Orthologues: chimpanzee SLC15A5 (98% identical), macaque SLC15A5 (95% identical), pig SLC15A5 (84% identical), dog SLC15A5 (82% identical), rabbit SLC15A5 (78% identical), guinea pig SLC15A5 (73% identical), mouse Slc15a5 (63% identical), rat Slc15a5 (63% identical), zebrafish slc15a5 (52% identical), tropical clawed frog SLC15A5 (50% identical). Paralogues in human: SLC15A3 (21% identical), SLC15A2 (19% identical), SLC15A4 (19% identical), SLC15A1 (18% identical).
Diseases named in the same sentence as SLC15A5 in open-access papers:
SLC15A5 is named in the same sentence as 3 diseases in open-access papers, as found by Europe PMC text mining. Sharing a sentence is not in itself a finding about the gene and the disease. The quoted sentences say what the papers report.
Obesity (1 paper, 2023). Accumulation of substantial excess body fat. "SLC15A5 is responsible for protein transport through membranes and LMO3 was shown to contribute to reprogramming of adipose tissue depots during obesity, thereby modulating nutrient homeostasis." (PMID 36980854, 2023).
SLC15A5 also shares sentences with these, for which no sentence is quoted: breast tumor (1 paper); pancreatic adenocarcinoma (1).